IL1B (interleukin 1 beta)
Diseases named in the same sentence as IL1B in open-access papers (continued):
Sharing a sentence is not in itself a finding about the gene and the disease.
gastric cancer (continued). "Information from clinical samples has proved that high expressions of IL-1β, IL-12, and IL-10 in macrophages or in plasma indicate poor progression of stomach cancer." (PMID 35382168, 2022). "The crucial role of IL-1β in gastric cancer pathogenicity was first described in a Mongolian gerbil model." (PMID 35683528, 2022). "In mice, gastric inflammation and, subsequently, gastric cancer can be induced by overexpression of IL-1β." (PMID 36293159, 2022). "The exposure of stomach-cancer cells to the medium from lipopolysaccharide (LPS)-treated macrophages significantly induced the production of IL-1β from stomach-cancer cells and promoted cell proliferation." (PMID 35382168, 2022). "NLRP3 inflammosomes enhance the differentiation of gastric cancer cells by participating in cyclin-D1 and inducing IL-1β production." (PMID 35153782, 2022). "In gastric cancer, IL-1β promotes DNA methyltransferase function via the synthesis of nitric oxide, resulting in promoter CpG island methylation-induced gene repression." (PMID 35757000, 2022). "All these results indicate the significant role of IL-1β, IL-12, and IL-10 in the tumor microenvironment in stomach cancer." (PMID 35382168, 2022). "Among them, IL-6 activates the STAT3 pathway, and IL-1β can reduce gastric acid secretion, ultimately leading to the development of H. pylori gastritis or even gastric cancer." (PMID 36249768, 2022). "MEK/ERK and transcription factors AP-1 and NFκB are all involved in CXCL8 upregulation by IL-1β in gastric-carcinoma cells and by CD40 in human fetal microglia." (PMID 35806457, 2022). "Increased IL-1β production aggravates development of gastric cancer by repressing secretion of gastric acid and orchestrating inflammatory response." (PMID 34707599, 2021). "GSDMD was also involved in inducing the release of inflammatory factors such as IL-1β and IL-18, which can promote the growth of gastric cancer cells and accelerate the formation of gastric tumors through immunosuppression." (PMID 34384029, 2021). "It was also demonstrated that IL-1β enhances migration and invasion in oral cancer and gastric cancer by down-regulating E-cadherin and up-regulating Snail." (PMID 34211462, 2021). "And a recent study demonstrated that inhibiting NLRP3 inflammasome and limiting IL-1β secretion were the main mechanisms of miR-22-induced decreased gastric cancer cells proliferation." (PMID 34211462, 2021). "The cascade of downstream pathways via activation of the NLRP3-mediated IL-1β axis has been found to activate NF-κB that initiates JNK signaling causing proliferation and invasion in gastric cancer." (PMID 33613533, 2020). "IL-1β can also act directly on gastric cancer cells and induces PI3K activation and translocation of S100A4, a factor known to be involved in the metastasis of several types of cancer." (PMID 32635472, 2020). "Overexpression of IL-1β in gastric cancer or fibrosarcoma models leads to accumulation of MDSCs at the tumor site." (PMID 32635472, 2020). "NLRP3-mediated IL-1β production activates NF-κB and initiates JNK signaling to cause proliferation in gastric cancer and CRC." (PMID 33613533, 2020). "NLRP3 enhances IL-1β, subsequently activating NF-κB, and initiates JNK signaling to cause proliferation and invasion in gastric cancer." (PMID 33613533, 2020). "SLFN12L+ myeloid cells express VEGF, IL-1β and TNF-α, which are known factors associated with MDSC regulation, an immunosuppressive cell of relevance to immunotherapy-resistant gastric cancer." (PMID 33348809, 2020). "A recent report demonstrated that inflammatory cytokines IL-1α, IL-1β or TNFα secreted by diffuse-type gastric cancer cells induced upregulation of rhomboid 5 homolog 2 (RHBDF2), also termed iRhom2 in cancer-associated fibroblasts (CAFs)." (PMID 32698506, 2020). "As shown in vitro with human gastric cancer cell lines, IL-1β increases macrophage recruitment by allowing monocyte chemoattractant protein (MCP)-1 expression by tumor cells." (PMID 32635472, 2020).
gastric cancer (continued). "An experiment carried out on the human gastric cancer AGS cell line confirmed the antioxidant properties of CORM-2 involving significant inhibition of IL-1β-induced ROS production." (PMID 32699258, 2020). "The expression of the tumor suppressive miR-7 in human gastric cancer inversely correlates with the levels of IL-1β and TNFα, suggesting that miR-7 down-regulation is related to the severity of inflammation and contributes to gastric tumorigenesis." (PMID 31557902, 2019). "Amongst these cytokines, IL-1β induced VEGF production in gastric cancer cells through Erk- and p38-dependent pathways, and IL-6 dose-dependently induced VEGF release from platelets, further linking the processes of inflammation with angiogenesis." (PMID 31757048, 2019). "In transgenic mice the expression of human IL-1β induced spontaneous gastric cancer, correlating with early recruitment of MDSC to the stomach." (PMID 30042333, 2018). "Collectively, these data indicated that exosomal MET promoted IL‐1β secretion from macrophages leading to gastric cancer progression though EMT." (PMID 30160350, 2018). "In mice, null mutants for IL-1β showed a 40% reduction in the expression level of p65, confirming the role of NF-κB in the inflammatory response in gastric cancer." (PMID 29315242, 2018). "There is a strong association between genetic polymorphisms in the interleukin (IL-)1β and IL-1 receptor gene cluster and in tumor necrosis factor (TNF)-α and the risk of gastric cancer." (PMID 30409143, 2018). "IL-1β methlylated cadherin through inhibition of NF-κB in H. pylori induced gastric cancer incidence." (PMID 29467412, 2018). "In consistent with this report, we found that gastric cancer cell-derived conditioned medium protected neutrophils from spontaneous apoptosis and induced IL-1β and TNFα expression, among other inflammatory factors." (PMID 30292233, 2018). "Intestinal type against to the diffuse or mixed-type of gastric cancer is more often in those with IL-1β-511T genotype." (PMID 30123433, 2018). "IL-1β is induced by a Helicobacter pylori infection, the most common chronic bacterial infection, and is the etiological agent for gastric cancer." (PMID 30042333, 2018). "What is more, the levels of mucosal IL-1β are higher in H. pylori-infected gastric cancer patients with IL-1β-31TT as against those with IL-1β-31CT and IL-1β-31CC." (PMID 30123433, 2018). "IL-1β is involved in the positive feedback loop of IL-1β/Akt/retinoic acid receptor α (RARα) signaling, and thereby transmits the oncogenic property of RARα in gastric carcinoma." (PMID 30042333, 2018). "For example, while H. Pylori infection is very common, only about 1% of infected people develop gastric cancer; this is due in large part to SNPs in the interleukin (IL)-1β gene that result in elevated IL-1β expression." (PMID 29186188, 2017). "IFN-γ and IL-10 levels were significantly higher in early (I/II) and late stage (III/IV) gastric cancer; IL-1β and IL-8 were higher and MCP-1 was lower only in late stage (IV) patients." (PMID 28558708, 2017). "Usually CagA+ strains promote higher production of IL1β and IL8 resulting in an increased risk of peptic ulcer and gastric cancer." (PMID 28932213, 2017). "Il-1β plays a pivotal proinflammatory role in H. pylori-induced gastric inflammation, DNA methylation, and gastric cancer." (PMID 27045955, 2016). "Polymorphisms in IL-1β, TNF-γ, and IL-10 are host-dependent genetic factors which also contribute to the multifactorial origin of gastric cancer." (PMID 26379360, 2015). "The link between IL-1β expression and gastric cancer progression in humans and murine models, has resulted in IL-1 receptor blockade being suggested as a novel therapeutic target in the effort to combat gastric cancer progression." (PMID 25528766, 2015).
gastric cancer (continued). "We have also showed that the presence of IL-1B-511 genotype for the inflammatory cytokine was inclined to the difference between intestinal type of gastric cancer, chronic gastritis and healthy controls." (PMID 26401131, 2015). "In gastric cancer cells, exogenous IL-1β stimulated MCP-1 expression, whereas IL-1Ra had an inhibitory effect." (PMID 24993819, 2014). "Spearman’s rank correlation test was used to analyze the correlation among Wnt5a, MCP-1 and IL-1β in gastric cancer tissues." (PMID 24993819, 2014). "Taken together, our results demonstrated that M.hy induced migration and invasion of gastric cancer cell line MGC-803 by promoting IL-1β secretion from monocytic cells." (PMID 24223129, 2013). "The H/K-ATPase-IL-1β mouse model of gastric cancer has been useful for elucidating the important contributions of stromal cells in the tumor microenvironments, including CAFs or inflammatory cells." (PMID 24216700, 2013). "Taken together, the IL-1β transgenic mouse model is considered to be one of the best mouse models of gastric cancer reported to date." (PMID 24216700, 2013). "Further in-depth research focused on IL-1B –511C/T and specific subtypes of gastric cancer is warranted." (PMID 23704929, 2013). "In HP-infected gastric cancer patients, the mucosal IL-1B level is higher in −31T carriers than in −31C carriers." (PMID 23704929, 2013). "We next determined the effect of human recombinant IL-1β (rIL-1β) on gastric cancer cell carcinogenesis in a colony formation assay,which revealed that the rIL-1β did not influence the proliferation of gastric cancer cell line MGC-803." (PMID 24223129, 2013). "In this study we have elucidated the signaling events that lead to IL1B-mediated repression of gastrin expression through NFkB activation in gastric carcinoma cells." (PMID 24009751, 2013). "Infection of H. pylori also disrupts gastric homeostasis and induces multiple inflammatory cytokine production within local mucosal, components such as IL-1β, TNF-α, and IL-10 genotypes are associated with increased risk for developing gastric cancer." (PMID 23217022, 2012). "Polymorphisms in genes coding pro-inflammatory cytokines, such as interleukin 1 beta (IL-1β), interleukin-1 receptor antagonist (IL1Ra) and tumor necrosis factor-alpha (TNF-α) are accepted as risk factors of gastric cancer, depending on the geographic region." (PMID 22891666, 2012). "For instance, cytokine polymorphisms of the IL-1β and TNF-α genes are associated with increased susceptibility to peptic ulcer disease and gastric cancer." (PMID 24212943, 2011). "In this study, we report that IL1B induces Smad 7 expression by about 4.5 fold in gastric carcinoma cell line, AGS." (PMID 21445336, 2011). "While most reports on IL1B are related to H. pylori infection and gastric cancer [39 for review] these studies have suggested that IL-1β is a critical link in inflammation as it leads to cancer." (PMID 21311097, 2010). "Pro-inflammatory IL1B and IL1RN polymorphisms are associated with increased risk of gastric carcinoma in Caucasian populations." (PMID 18842150, 2008). "The overall frequencies of IL-1B-31 T, -511 T, +3954 T and IL-1RN VNTR alleles in patients with locally advanced gastric cancer were all comparable with those in controls." (PMID 17359523, 2007). "In view of the inflammatory nature of cancer cachexia, we determined the predictive value of IL-1B-31 T/C, -511 C/T, +3954 C/T and IL-1RN VNTR gene polymorphisms on the occurrence of cachexia associated with locally advanced gastric cancer." (PMID 17359523, 2007). "Given PPARα’s established role in restraining pro-inflammatory cytokines such as IL-6, IL-1β, and TNF-α, and the importance of inflammation in gastric cancer progression, we next assessed whether loss of PPARα elevates inflammatory mediators in GC cells." (PMID 40732023, 2025).
gastric cancer (continued). "Thus, considering all this, the objective of this study was to determine the effect of Triptolide on IL-1β-induced IL-8 expression in gastric cancer by modulating ROS-mediated AP-1/NF-κB and ERK signaling." (PMID 39950099, 2024). "As the known pro-inflammatory cytokines inducing gastric cancer, IL-1β and TNF-α mediate H. pylori to initiate a large number of neutrophils and lymphoid cells to infiltrate gastric mucosa, highly polarized to Th1 cytokine response, leading to gastric mucosal injury and disease." (PMID 38774627, 2024). "This suggests that IL-1β may have a synergistic effect with IL-4 in promoting immunotherapy resistance of gastric cancer through macrophages." (PMID 39003253, 2024). "Much evidence has shown that IL-1β is related to the development of gastric cancer." (PMID 38182564, 2024). "Specifically, IL-1β can promote gastric cancer cell growth by the tyrosine kinase pathway." (PMID 38444674, 2024). "IL-1β activates transcription factor p65 of gastric cancer to up-regulate INHBB expression." (PMID 37858201, 2023). "IL-1β was found to induce miR-425 expression in gastric cancer cells by activating NF-κB signaling." (PMID 37834058, 2023). "In the present study, PF treatments inhibited inflammatory markers such as TNF-α, IL-6, and IL-1β in LPS-treated Raw264.7 cells and induced apoptotic cell death by activating the ER stress signaling pathway and releasing intracellular ROS in gastric cancer cells." (PMID 38140352, 2023). "HP infection is considered the strongest single risk factor for gastric cancer and NLRP3 may be involved via the production of IL-1β." (PMID 37081882, 2023). "Furthermore, studies have demonstrated that levels of IL-1β, IL-6, and IL-8 in gastric cancer tissues are significantly elevated in H. pylori-positive cases compared to H. pylori-negative cases." (PMID 37729185, 2023). "Similarly, in gastric cancer, the IL-1β/NF-κB axis has been demonstrated to upregulate the expression of miR-425, which can promote the growth of gastric cancer cells by negatively regulating PTEN." (PMID 35267528, 2022). "Our study illustrated that DLL3 in stomach cancer could induce IL-1β, IL-12, and IL-10 secretion of macrophages via up-regulating IL-33." (PMID 35382168, 2022). "We demonstrate increased IL-1β involvement in our Tipα stimulated gastric cancer cells model." (PMID 35237167, 2022). "In terms of gastric cancer, IL-1β, which is strongly involved in the activation of NF-κB, has the ability to stimulate the proliferation of malignant gastric tumor cells through a tyrosine kinase pathway, which is associated with granulocyte-macrophage colony-stimulating factor." (PMID 35884067, 2022). "It was reported that IL-1β could induce an increase in the DNMT activity via NF-κB pathway in gastric cancer cells and TGF-β1 could up-regulate the expression of DNMT1 and 3a though different mechanisms including activation of the PI3K/Akt pathway." (PMID 35265687, 2022). "IL-1β promotes gastric cancer cell line proliferation via the tyrosine kinase pathway." (PMID 35892729, 2022). "Lin proposed that the genetic polymorphisms of IL1B-511 and IL1B-31 in a Han Chinese population were associated with susceptibility to gastric cancer, and clinical tests showed that the T type of IL1B-511 or the C type of IL1B-31 increased the incidence rate of gastric cancer." (PMID 36200190, 2022). "We found MK2 expression to be linked to gastric cancer metastasis and nine significant cytokine associations, including MK2-dowstream cytokines, IL-1β, IL-6, and TNFα along with other previously unrecognized cytokines linked to MK2; G-CSF, GM-CSF, Mip-1β, IFN-α, MCP-1, and IL-2." (PMID 32216812, 2020). "In addition, stomach specific expression of mature human IL-1β in mice developed the stepwise progression of gastric inflammation, dysplasia and gastric cancer and Th1 specific immunity promoted this process." (PMID 32230726, 2020).
gastric cancer (continued). "IL1B-511T carriers, suggesting higher expression of IL1B, present a higher risk of developing gastric cancer, or not." (PMID 32635472, 2020). "Of particular interest is that we found IL-1β to be highly correlated with MK2 expression, suggesting this cytokine in particular to be critical in association with MK2 expression and subsequently gastric cancer metastasis." (PMID 32216812, 2020). "The penetrance rates of genetic polymorphisms in pro-inflammatory genes (IL1B, IL8, TNFA, etc.)and PSCA (Prostate Stem Cell Antigen) are low (probably less than 5%) for sporadic gastric cancer, which accounts for more than 90% of gastric cancer." (PMID 31035365, 2019). "In addition, several studies have shown that IL-1β is involved in the development of gastric cancer." (PMID 31832112, 2019). "Furthermore, transgenic mice that overexpress IL-1β developed gastric inflammation and gastric cancer, a response also found in transgenic mice expressing a constitutively active AhR." (PMID 31035533, 2019). "Among them, it has to be emphasized polymorphisms in genes involved in the adaptive immune response such as the IL-1β cytokine and in members of the host’s innate immune response, Toll-like receptor-4 (TLR-4), which are associated with increased risk of gastric cancer." (PMID 30630444, 2019). "Furthermore, the supernatant from gastric cancer cells induced IL-1β and TNFα expression in neutrophils and prolonged the half-life of neutrophils." (PMID 30292233, 2018). "Indeed Helicobacter pylori is etiologically involved in the development of gastric cancer and infected gastric mucosa has been shown to possess elevated levels of cytokines, for example, interleukin (IL-1β, IL-6, and IL-8)." (PMID 28050120, 2016). "The pooled analysis did not suggest the significant association of IL‐1B 31 C>T polymorphism with gastric cancer risk." (PMID 26805397, 2016). "Some studies provided evidence of the association between IL‐1B 31 polymorphism and gastric cancer risk while other studies did not." (PMID 26805397, 2016). "In this meta‐analysis of 37 studies including 6000 cases and 8483 controls, we did not provide evidence of the association between IL‐1B 31 polymorphism and gastric cancer." (PMID 26805397, 2016). "The symmetrical funnel plots suggested no publication bias for the association between IL‐1B 31 polymorphism and overall gastric cancer risk under all the genetic models." (PMID 26805397, 2016). "Carriers of the proinflammatory IL-1B-511*T allele (both IL-1B-511T homozygotes and IL-1B-511 heterozygotes) had also no increased risk for gastric cancer (OR = 1.570; 95% CI: 0.644–3.825) or chronic gastritis (OR = 0.480; 95% CI: 0.232–0.996)." (PMID 26401131, 2015). "For PTPN11 rs12229892 and IL1B rs1143623, rs1143623 GC/CC genotypes were associated with a reduced gastric cancer risk only in the absence of rs12229892 GA/AA genotypes." (PMID 26158864, 2015). "The SNPs at position −31 (T<C) of IL-1B result in the inhibition of gastric acid secretion and have been associated with noncardia and intestinal-type gastric cancer among Caucasians." (PMID 26379360, 2015). "In summary, we observed novel SNP interactions among PGC, PTPN11, and IL1B which modified the risks of gastric cancer and atrophic gastritis and we provided important hints of effect modification by H. pylori infection on the cumulative effect of PGC rs6912200, PGC rs4711690, and PTPN11 rs12229892." (PMID 26158864, 2015). "The CagA-mediated inflammasome activation may provide a mechanistic link between H. pylori CagA and IL-1β in the development of gastric cancer." (PMID 25944120, 2015). "The inhibition of IL-1β after pSTAT3 inhibition by WP1066 is particularly significant, because IL-1β is an important regulator of gastric acid secretion, a potent promoter of tumour growth in a transgenic mouse model of gastric cancer, and an integral part of the NLRP3 inflammasome." (PMID 24804649, 2014).